CAMK4 (calcium/calmodulin dependent protein kinase IV)
Diseases named in the same sentence as CAMK4 in open-access papers (continued):
Sharing a sentence is not in itself a finding about the gene and the disease.
Alzheimer disease (4 papers, 2016 to 2022). A progressive, neurodegenerative disease characterized by loss of function and death of nerve cells in several areas of the brain leading to loss of cognitive function such as memory and language. "CAMK4 is upregulated in Alzheimer’s disease patients and associated with mitochondrial dysfunction and neuroinflammation." (PMID 36079709, 2022).
Cognitive impairment (4 papers, 2012 to 2025). Abnormal cognition is characterized by deficits in thinking, reasoning, or remembering. "CAMK4 has been implicated as mediator of CREB-dependent transcription and synaptic plasticity, and its inhibition has been reported to alleviate cisplatin-induced cognitive deficits." (PMID 41226340, 2025). "Additionally, β-carotene intake could help to mitigate brain fog or cognitive impairment through its effect on calcium/calmodulin-dependent protein kinase IV (CAMKIV)." (PMID 37891835, 2023).
neuroblastoma (4 papers, 2019 to 2024). Neuroblastoma (NB) is the most common solid, extracranial childhood tumor. "A latest finding also indicated that CAMK4 could inhibit the proliferation of HepG2 and neuroblastoma cells (SH-SY5Y) by combining with Vanillin to increase the viability of CAMK430." (PMID 31624237, 2019).
autism (3 papers, 2017 to 2025). Persistent deficits in social interaction and communication and interaction as well as a markedly restricted repertoire of activity and interest as well as repetitive patterns of behavior. "In this context, several genes downregulated in the brainstem of Hoxa5 cKO mouse at P21, such as Grm4, Cbln1, En2, Camk4, and Cadps2, have been associated to autism traits either in humans or in mouse models." (PMID 29187810, 2017). "Consistently, the Simons Foundation Autism Research Initiative (SFARI) gives CAMK4 a SFARI Gene Score of two, signifying it as a strong candidate autism risk gene." (PMID 41007373, 2025). "Although CAMK4 is known to encode a serine/threonine protein kinase involved in a Ca2+-calmodulin dependent pathway that regulates synaptic plasticity and other neuronal functions, experimental evidence linking CAMK4 function with autism-related phenotypes remains elusive." (PMID 41007373, 2025). "The calcium/calmodulin-dependent protein kinase IV (CAMK4, MIM*114080) gene encodes an important mediator of calcium-mediated activity and dynamics, particularly in the brain, and it is presented as a strong candidate for autism in the SFARI database (score: 2)." (PMID 37510409, 2023).
diabetes (3 papers, 2010 to 2024). "However, there is very limited evidence about genetic variation on CAMK4 or FMN1 and diabetes or its complications." (PMID 20871662, 2010).
Intellectual disability (3 papers, 2018 to 2022). "Interestingly, mutations of orphan nuclear receptor genes have been discovered to result in neurodevelopmental delay, intellectual disability, and cerebellar atrophy–associated motor anomalies, features also coincident with the CAMK4 mutation identified here." (PMID 30262571, 2018). "The gene–disease analysis further revealed that the ATP6V1A/BNIP3 and CAMK4/TIPRL/TOMM70 signatures were associated with several brain-related disorders, including developmental disabilities, schizophrenia, intellectual disabilities, abnormal cerebral white matter morphology, and mental retardation." (PMID 34683848, 2021).
ischemic stroke (3 papers, 2013 to 2020). A stroke disorder caused by obstruction of blood flow to the brain, due to thrombotic (local blood clot formation) or embolic (due to a blood clot or other material traveling from another site) event. "Increased HDAC4 nuclear shuttling was observed in the neurons of ischemic stroke model mice/ats and in oxygen-glucose deprivation (OGD)-treated neurons, while the overexpression of calcium/calmodulin-dependent protein kinase IV (CaMKIV) reduced the levels of nuclear HDAC4 in ischemic stroke." (PMID 30208931, 2018).
myeloid leukemia (3 papers, 2018 to 2022). A clonal proliferation of myeloid cells and their precursors in the bone marrow, peripheral blood, and spleen. "In myeloid leukemia cells and macrophages, CaMK4 phosphorylates and inhibits GSK3β, preventing proteasomal degradation of mTOR." (PMID 36002021, 2022). "The infiltration of Camk4-null myeloid leukemia cells into the liver and spleen was significantly decreased." (PMID 29482582, 2018).
psoriasis (3 papers, 2022 to 2025). An autoimmune condition characterized by red, well-delineated plaques with silvery scales that are usually on the extensor surfaces and scalp. "In summary, our present study provides evidence of the mechanism underlying CaMK4 in the pathogenesis of psoriasis." (PMID 35869084, 2022). "Camk4-deficient (Camk4−/−) mice treated with IMQ exhibit reduced severity of psoriasis compared to wild-type (WT) mice." (PMID 35869084, 2022). "Studies have shown that the expression of CaMK4 is significantly increased in the skin lesions of psoriasis patients." (PMID 40766324, 2025). "The mRNA level of CAMK4 was also higher in the cells of peripheral blood of patients with psoriasis than in that of healthy controls." (PMID 35869084, 2022). "Then, we established a classic IMQ-induced psoriasis mouse model using Camk4−/− and WT (Camk4+/+) mice." (PMID 35869084, 2022). "We subsequently analyzed the relationships between the expression of pro-inflammatory cytokines and CAMK4 expression in the cells of peripheral blood from patients with psoriasis using correlation analysis." (PMID 35869084, 2022). "Here, we demonstrate that CaMK4 expression is significantly increased in psoriatic lesional skin from patients with psoriasis and mice with IMQ-induced psoriasis compared to healthy skin." (PMID 35869084, 2022). "The severity scoring and histological analysis showed that the severity of psoriasis was alleviated in IMQ-treated Camk4−/− mice compared to IMQ-treated Camk4+/+ mice." (PMID 35869084, 2022). "Here the authors show that CaMK4 is increased in psoriasis and promotes inflammatory responses in mouse models of psoriasis mediated through macrophages and keratinocytes." (PMID 35869084, 2022). "The mechanism of CaMK4 affecting psoriasis is mediated by γδ T17 cells, which is different from the function of Th17 cells in SLE." (PMID 35869084, 2022). "Calcium, as an important second messenger, may play a crucial role in the pathogenesis of psoriasis by regulating signaling pathways such as calcium/calmodulin-dependent protein kinase IV (CaMK4) and calcium/calmodulin-dependent protein kinase II-γ (CaMK2γ)." (PMID 40766324, 2025). "In addition to the reported effect of CaMK4 on IL-17A production, we also document that CaMK4 has functions in dermal macrophages and epidermal KCs to affect psoriasis progression." (PMID 35869084, 2022). "Understanding the mechanism by which CaMK4 affects the pathogenesis of psoriasis may lead to the development of therapeutic strategies for psoriasis." (PMID 35869084, 2022). "Briefly, these data suggest that the reduction of the severity of IMQ-induced psoriasis by KN-93 is mainly caused by the inhibition of CaMK4 rather than CaMK2." (PMID 35869084, 2022). "Collectively, our data show that CaMK4 has critical functions in monocytes, including promoting pro-inflammatory cytokine production and inhibiting anti-inflammatory cytokine production, thus affecting psoriasis progression." (PMID 35869084, 2022). "Here, we show that CaMK4 expression is significantly increased in psoriatic lesional skin from psoriasis patients compared to healthy human skin as well as inflamed skin from an imiquimod (IMQ)-induced mouse model of psoriasis compared to healthy mouse skin." (PMID 35869084, 2022). "However, CaMK4 expression was higher in CD14+ monocytes from both patients with psoriasis and healthy controls than in T cell subsets." (PMID 35869084, 2022). "The expression of many genes known to be associated with psoriasis, including Lce3f, Sprr2b, Krt15, S100a8, S100a9, Il17a, Il17f, Il18, Il20, Il22, and Ccl20, was downregulated in the skin of IMQ-treated Camk4−/− mice compared with those of IMQ-treated Camk4+/+ mice." (PMID 35869084, 2022). "Therefore, we focused on macrophages and speculated that CaMK4 promotes psoriasis by controlling macrophages." (PMID 35869084, 2022).
psoriasis (continued). "To confirm the mechanism by which CaMK4 inhibits IL-10 production through the Erk1/2 and p38 pathways found in mouse macrophages, we sorted peripheral CD14+ monocytes from patients with psoriasis." (PMID 35869084, 2022). "To better understand the contribution of CaMK4 in psoriasis, we first detected CaMK4 expression in patients with psoriasis and mice with IMQ-induced psoriasis by various methods." (PMID 35869084, 2022). "In addition, we found that CaMK4 expression was increased in F4/80+ cells, CD11c+ cells, and primary KCs but not in B cells and neutrophils from IMQ-treated mouse skin compared to healthy mouse skin, suggesting that CaMK4 may function in myeloid cells and KCs to influence IMQ-induced psoriasis." (PMID 35869084, 2022). "We found that the proportion of CaMK4+ cells and the mean fluorescence intensity (MFI) of CaMK4 were both higher in peripheral T cell subsets (CD4+, CD8+, and double-negative (DN) cells) and CD14+ monocytes from patients with psoriasis than in those from healthy controls." (PMID 35869084, 2022).
allergic disease (2 papers, 2017 to 2020). An immune response that occurs following re-exposure to an innocuous antigen, and that requires the presence of existing antibodies against that antigen. "Some of these genes have a known function that is relevant to allergic disease, including F11R, CD247, PGAP3, AAGAB, CAMK4 and PEX14, and so could be prioritized for functional follow-up." (PMID 29333270, 2017).
colitis (2 papers, 2016 to 2022). Inflammation of the colon. "Activation of calcium/calmodulin-dependent protein kinase IV (CaMKIV) has been shown to increase Dextran Sulfate Sodium-induced intestinal injury and inhibit epithelial cell proliferation in mice with colitis." (PMID 35575464, 2022).
endometrial carcinoma (2 papers, 2019 to 2021). A malignant tumor arising from the epithelium that lines the cavity of the uterine body. "Furthermore, high CAMK4 expression is associated with significantly worse overall survival for AML patients, and in endometrial carcinoma." (PMID 30621060, 2019).
epilepsy (2 papers, 2021 to 2023). A brain disorder characterized by episodes of abnormally increased neuronal discharge resulting in transient episodes of sensory or motor neurological dysfunction, or psychic dysfunction. "Overexpression of miR-125a-5p attenuated epilepsy and decreased inflammatory factor levels in the hippocampus by suppressing calmodulin-dependent protein kinase IV (CAMK4), suggesting that miR-125a-5p might represent a novel treatment for epilepsy." (PMID 33776649, 2021).
experimental autoimmune encephalomyelitis (2 papers, 2016 to 2018). An autoimmune demyelinating disease of the central nervous system that is produced experimentally in animals by the injection of homogenized brain or spinal cord in Freund's adjuvant. "Moreover, mice lacking CaMK4 or mice subject to pharmacological inhibition of CaMK4 are resistant to experimental autoimmune encephalomyelitis (EAE), which has been well established that it depends on Th17 cells." (PMID 30333818, 2018).
injury (2 papers, 2020 to 2022). Damage inflicted on the body as the direct or indirect result of an external force, with or without disruption of structural continuity. "The results revealed that CGGE could maintain glutamate and GABA balance via activating CAMK4/CREB pathway, which plays a vital role in maintaining normal neural function and reducing secondary brain injury." (PMID 36091745, 2022).
Insulin resistance (2 papers, 2020 to 2024). Increased resistance towards insulin, that is, diminished effectiveness of insulin in reducing blood glucose levels. "Increased lipid deposition in tissues is closely associated with insulin resistance, and CAMK4 enhances insulin sensitivity and indirectly modulates lipid metabolism." (PMID 38203803, 2024).
lupus nephritis (2 papers, 2018 to 2022). Glomerulonephritis in the context of systemic lupus erythematosus. "They further demonstrated that CaMK4 expression is increased in podocytes of patients of active lupus nephritis and transplant glomerulopathy." (PMID 35333675, 2022). "Although in lupus nephritis it appears that IgG that enters podocytes elicits an increase in the expression of CaMK4, the involved mechanism is still at large." (PMID 30333818, 2018). "Podocytes from lupus nephritis patients exhibit elevated levels of CaMK4." (PMID 30333818, 2018). "Interestingly, CaMK4 also plays a role in resident kidney cells and contributes to the pathogenesis of lupus nephritis by promoting mesangial cell proliferation through IL-6 production." (PMID 30333818, 2018). "It appears that delivery of a CaMK4 inhibitor to podocytes holds high therapeutic promise for both immune (lupus nephritis) and non-immune (FSGS) podocytopathies." (PMID 30333818, 2018). "Therefore, targeted delivery of a CaMK4 inhibitor to podocytes holds high therapeutic promise for both immune (lupus nephritis) and non-immune (FSGS) podocytopathies." (PMID 30333818, 2018).
abortion (1 paper, 2024). the ending of pregnancy by removing a fetus or embryo before it can survive outside the uterus. "A recent study conducted on a mouse model of abortion has shown that CaMK4 is essential for the regulation of Th17 cell infiltration and associated cytokine production at the maternal–fetal interface through the AKT/mTOR pathway." (PMID 39051375, 2024).
amyotrophic lateral sclerosis (1 paper, 2024). Amyotrophic lateral sclerosis (ALS) is a neurodegenerative disease characterized by progressive muscular paralysis reflecting degeneration of motor neurons in the primary motor cortex, corticospinal tracts, brainstem and spinal cord. "Both kinases have been connected with neuronal survival or protection, since CaMK2 has been reported to protect retinal ganglion cells in glaucoma, while CaMK4 promotes neural survival and is reduced in neurodegenerative diseases, such as amyotrophic lateral sclerosis." (PMID 38542418, 2024).
autism spectrum disorder (1 paper, 2025). A spectrum of developmental disorders that includes autism, and Asperger syndrome. "CAMK4 (calcium/calmodulin-dependent protein kinase 4) has recently been identified as a risk gene for autism spectrum disorder." (PMID 41007373, 2025). "CAMK4 has recently been linked to autism spectrum disorder (ASD), a condition that affects social behavior and is often accompanied by sleep problems and motor difficulties." (PMID 41007373, 2025).
autosomal dominant polycystic kidney disease (1 paper, 2023). Autosomal dominant form of polycystic kidney disease. "In human autosomal dominant polycystic kidney disease cells, the knockdown of CaMK4 or the inhibition of CaMK4 by KN-93 reportedly decreased S6K1 phosphorylation and cell proliferation." (PMID 36835331, 2023).
bipolar disorder (1 paper, 2023). A disorder of the brain that causes unusual shifts in mood, energy, activity levels and the ability to carry out day-to-day tasks. "Furthermore, a recent study of genetic variants associated with lithium responsiveness in bipolar disorder patients found a significant enrichment of genes involved in glutamatergic synapse neurotransmission, which included GSK3 and CAMK4." (PMID 37730845, 2023).
cerebral malaria (1 paper, 2013). A sequestration of Plasmodium falciparum in the brain, which can cause coma and/or seizures. "Of particular interest were 3 brain-specific proteins found in plasma namely brain-specific angiogenesis inhibitor 2, calcium/calmodulin-dependent protein kinase IV in acute bacterial meningitis, and spectrin nonerythroid β chain 3 in cerebral malaria." (PMID 23888081, 2013).
cyst (1 paper, 2022). A sac-like closed membranous structure that may be empty or contain fluid or amorphous material. "The effects of metformin on AMPK activation, mTOR inhibition, and in vitro cyst formation were significantly enhanced by CaMK4 inhibition with KN-93." (PMID 36002021, 2022). "By contrast, age- and sex-matched ADPKD tissue sections showed intense CaMK4 staining in both the cytoplasm and nuclei of cyst-lining epithelial cells (inset) and interstitial cells adjacent to cysts (asterisk)." (PMID 36002021, 2022). "Here, we showed that inhibition of CaMK4 and its upstream regulators, CaMKKβ and CaM, individually inhibited mTOR activity and in vitro cyst growth of the ADPKD cells." (PMID 36002021, 2022). "Pharmacologic inhibition of CaMK4 with KN-93 reduced phosphorylated S6K and S6 levels and inhibited cell proliferation and in vitro cyst formation of ADPKD cells." (PMID 36002021, 2022). "To investigate the role of CaMK4, we knocked down CaMK4 expression using shRNA and examined the effects of KN-93, a CaMK4 inhibitor, on mTOR signaling, cell proliferation, and in vitro cyst formation in human ADPKD cells." (PMID 36002021, 2022). "Our data show that CaMK4 is a novel upstream regulator of mTOR and that CaMK4 inhibition may be a therapeutic approach to slowing cyst growth in ADPKD patients." (PMID 36002021, 2022). "Elevated CaMK4 expression in cyst-lining cells of human ADPKD, ARPKD, and rodent models of PKD indicates that CaMK4 overexpression is a common feature of renal cystic disease regardless of the gene mutation." (PMID 36002021, 2022). "Pharmacologic inhibition of CaMK4 with KN-93 reduced levels of P-S6K and P-S6, and inhibited ADPKD cell proliferation and in vitro cyst growth." (PMID 36002021, 2022).
cystic kidneys (1 paper, 2022). "CaMK4 expression was also elevated in the interstitium adjacent to cysts, possibly due to the activation of inflammatory cells in the cystic kidneys." (PMID 36002021, 2022).
dependence (1 paper, 2012). "The calcium activated protein, calcium/calmodulin-dependent protein kinase IV (CaMKIV) phosphorylates the downstream transcription factor cyclic AMP response element binding protein (CREB), which mediates nicotine responses; however the role of CaMKIV in nicotine dependence is unknown." (PMID 23226481, 2012).
focal segmental glomerulosclerosis (1 paper, 2018). A renal disorder characterized by sclerotic lesions in the glomeruli. "CaMK4 is also upregulated in podocytes from patients with focal segmental glomerulosclerosis (FSGS)." (PMID 30333818, 2018).
frontotemporal dementia (1 paper, 2020). Frontotemporal dementia (FTD) comprises a group of neurodegenerative disorders, characterized by progressive changes in behavior, executive dysfunction and language impairment, as a result of degeneration of the medial prefrontal and frontoinsular cortices. "CAMK4, a member of the family of calcium/calmodulin-dependent kinases was also found oppositely regulated to GFAP in the neocortex of frontotemporal dementia-like mice with TDP-43 depletion." (PMID 32138778, 2020).
glomerular disease (1 paper, 2021). "To evaluate whether this phenotype is associated with glomerular disease in patients with SLE, we examined the expression of CaMK4 and nephrin in kidney biopsies from 30 patients referred to our center for suspected LN between 2017 and 2018." (PMID 33784256, 2021).
glomerulosclerosis (1 paper, 2012). A hardening of the kidney glomerulus caused by scarring of the blood vessels. "We also found renal damage, another typical feature of the hypertensive phenotype, inasmuch as CaMK4−/− mice displayed increased glomerulosclerosis, inflammatory cell infiltration, and tubulointerstitial fibrosis compared with CaMK4+/+ mice." (PMID 23130158, 2012).
Hepatic fibrosis (1 paper, 2023). The presence of excessive fibrous connective tissue in the liver. "Fgfr3, Camk4, Gpx4, Hoxd3, and Prkcb were verified to be hyper-methylated in hepatic fibrosis of mice induced by CCl4 for 8 weeks." (PMID 36594057, 2023).